KRAS (KRas proto-oncogene, GTPase)
Diseases named in the same sentence as KRAS in open-access papers (continued):
Sharing a sentence is not in itself a finding about the gene and the disease.
pancreatic cancer (continued). "In accordance with our findings, a recent report demonstrates that oncogenic KRAS requires EGF stimulation for enhanced activity in pancreatic cancer cells: EGF induced a prolonged activity of oncogenic KRAS, whereas only transient effects are seen in cells with wild type KRAS." (PMID 25992771, 2015). "The downregulation of SOX2 by 6-MITC and I7557 in PANC-1 pancreatic cancer cells harboring mutant K-ras may shed light on elucidating the interaction between SOX2, EGFR, and its downstream KRAS/BRAF and PI3K/AKT pathways." (PMID 24575144, 2014). "Recently, our lab has shown that in pancreatic cancer KRAS utilizes GSK3α to promote both canonical and non-canonical NF-κB activation." (PMID 24955217, 2014). "Higher frequency of KRAS, P16 and SMAD4 mutations in extrahepatic CCA suggest a molecular phenotype that resembles pancreatic cancer rather than intrahepatic CCA." (PMID 25536104, 2014). "Significant RBM5 underexpression and KRAS overexpression were observed in pancreatic cancer compared to non-tumor tissues." (PMID 23425895, 2013). "Consistent with other studies, our results revealed that pancreatic cancer tissues are presented with elevated KRAS expression compared to non-tumor tissues." (PMID 23425895, 2013). "First, we have showed that the sensitivity of pancreatic cancer cell lines toward either PI3K or MEK inhibitors is not KRAS dependent." (PMID 24130864, 2013). "Direct targeting of KRAS has not been successful in patients with pancreatic cancer, so current research efforts have refocused on two downstream pathways, the phosphatidylinositol 3-kinase (PI3K)/AKT pathway and the RAF/MEK pathway." (PMID 24130864, 2013). "With these data, we speculate that DCLK1 plays a role in post-transcriptional regulation of miR-143/145 cluster and thereby downregulates KRAS and RREB1 in pancreatic tumor xenografts." (PMID 24040120, 2013). "Mutant KRAS, for example, is readily detected in pancreatic juice but can be identified in the circulation only at the stage of non-resectable pancreatic cancers." (PMID 22458520, 2012). "In complementary experiments, we attempted to overexpress GATA6 by retroviral transduction in nontumorigenic human pancreatic ductal epithelial HPDE cells, and in the pancreatic cancer cell line PL45 harboring activated KRAS but no 18q11.2 gain." (PMID 18535672, 2008). "We show that depletion of WT Kras in Kras mutant mice facilitates tumorigenesis in the pancreas yet was not sufficient to drive progression to PDAC, suggesting that WT KRAS acts to restrain mutant KRAS signaling but does not act as tumor suppressor in pancreatic cancer." (PMID 39412982, 2025). "In addition, in the KPC mouse model, a more aggressive model of pancreatic cancer, lack of WT KRAS led to accelerated initiation but delayed tumor progression." (PMID 39412982, 2025). "In fact, in pancreatic cancer cells, mutant KRAS activates DYRK1B via RAC1, a member of the RHO family and the combinatory depletion of DYRK1B and KRAS led to strongly reduced cancer cell viability, which is of high interest in light of recently developed small molecule KRAS inhibitors." (PMID 39863750, 2025). "Thus, so far, the allelic status of KRAS is not included in the decision-making in terms of the therapeutic options and strategies for either resectable or advanced pancreatic cancer." (PMID 40227826, 2025). "Notably, 28 μg/ml of liposome-GGTI combined with 2.5 μM FTI suppressed cell proliferation by approximately 80% in KRAS mutant pancreatic cancer cells—an effect neither agent achieved on its own." (PMID 40335986, 2025). "In addition to renal cancer, in pancreatic cancer cells, the deletion of SETD2 will promote the reorganization of acinar to ductal metaplasia (ADM) of pancreatic acinar cells driven by the oncogene KRAS, which is mainly mediated by F-box and WD repeat domain protein 7 (Fbxw7)." (PMID 40786181, 2025).
pancreatic cancer (continued). "There are currently several recruiting clinical trials for VS-6766 in combination with: adagrasib (in KRAS G12C NSCLC patients; NCT05375994), sotorasib (in KRAS G12C NSCLC patients; NCT05074810) or defactinib with gemcitabine and nab-paclitaxel (in patients with pancreatic cancer; NCT05669482)." (PMID 40597785, 2025). "However, virtually all pancreatic ductal adenocarcinoma (PDA) express oncogenic KRas, indicating that this oncogene is necessary but not sufficient for progression from premalignant lesions to pancreatic cancer." (PMID 39627248, 2024). "Most pancreatic adenocarcinomas have KRAS alterations, which have been shown to be a marker of resistance to HER2-targeted therapies in other malignancies, though the impact of these alterations in pancreatic cancer is unknown." (PMID 38406801, 2024). "Notably, among the eight evaluable patients with pancreatic tumors in FIGHT-207, seven patients had FGFR fusions in the context of the KRAS wild-type background, highlighting the importance of testing for FGFR2 fusions in this population with few therapeutic options." (PMID 38710951, 2024). "KRB-456 binds with high affinity to KRAS G12D and KRAS G12V, decreases the cellular levels of GTP-bound KRAS, inhibits the binding of KRAS to RAF1 in pancreatic cancer cells, and inhibits in vivo tumor growth of subcutaneous and orthotopic xenografts from patients with pancreatic cancer." (PMID 38051103, 2023). "By targeting specific molecular biomarkers, such as EGFR, BRCA1, KRAS, and HER2, tailored nanocarrier formulations have shown promising clinical outcomes in patients with various cancer types, including non-small cell lung cancer, breast cancer, and pancreatic cancer." (PMID 37814270, 2023). "However, combination treatment with MEK and SHP2 inhibitors resulted in the continued regression of tumor growth in xenograft models of pancreatic cancer and NSCLC derived from patients, indicating the clinical efficacy of dual SHP2/MEK inhibition for KRAS-mutant cancers." (PMID 37662925, 2023). "In pancreatic cancer, ARID1A deletion promotes pancreatic tumorigenesis by increasing chromatin accessibility to the enhancer region of aldehyde dehydrogenase 1 family member A1 (ALDH1A1), upregulating ALDH1A1 expression, and attenuating KRAS-induced senescence." (PMID 35965507, 2022). "Pancreatic tumor cells metabolize Gln via a nonclassical pathway, which is mediated by KRAS." (PMID 35743139, 2022). "However, KRAS-mutant pancreatic cancer cells are sensitive to erastin or RSL3-induced ferroptosis, suggesting that KRAS may be a ferroptosis suppressor in pancreatic cancer cells." (PMID 35992146, 2022). "In conclusion, our findings clearly indicate that the expression of oncogenic KRAS shifts the balance of DSB repair towards the highly error-prone alt-EJ pathway, and highlights the mutagenic properties of alt-EJ, making it the preferred DNA repair pathway in pancreatic cancer." (PMID 36077614, 2022). "To investigate whether MYEOV acts as ceRNA to exert certain regulatory effects on genes such as GPRC5A, SERPINB5, KRAS, EGFR, EIF4G2, and PDCD4, we analyzed the differential expression of these genes in pancreatic cancer and normal pancreatic tissues by the GEPIA database." (PMID 36358856, 2022).
pancreatic cancer (continued). "CtDNA detection using liquid biopsy (droplet digital PCR (ddPCR) utilizing KRAS G12/13 and, if negative, Q61 commercial test kits) was prospectively performed on patients with stage IV pancreatic cancer i) prior to initiation of systemic chemotherapy and ii) serially every 2 weeks until restaging." (PMID 36110940, 2022). "Interestingly, KRAS‐mutant colon cancer cells appear to show a greater dependency on PLK1 for survival than KRAS‐mutant lung and pancreatic tumor cells, as single treatment with PLK1 inhibitors (e.g., BI2536) is sufficient to induce high levels of ROS and activation of the p38/JNK/E2F1 axis." (PMID 34369083, 2021). "Based on novel gene fusions involving NRG1 that we recently discovered in a series of patients with KRAS wild-type pancreatic tumors in the context of NCT/DKTK MASTER, a HTS-guided precision oncology program, we applied Arriba to further explore the relevance of gene fusions in pancreatic cancer." (PMID 33441414, 2021). "To date, KRAS is not a viable therapeutic target for pancreatic cancer." (PMID 33408779, 2021). "Furthermore, the EGFR signaling is required to initiate the KRAS oncogene-driven PanIN lesions and PDAC, and may be the possible reason that erlotinib exerts therapeutic effects for patients with pancreatic cancer." (PMID 34360896, 2021). "Pancreatic cancer is a devastating disease with a poor survival rate, and oncogenic mutant KRAS is a major driver of its initiation and progression; however, effective strategies/drugs targeting major forms of mutant KRAS have not been forthcoming." (PMID 33668583, 2021). "Caution is advised, however, in light of evidence that KRAS inhibition using CRISPR/Cas9–mediated gene editing of oncogenic KRAS may be dispensable for a subset of pancreatic cancer cell clones that are able to survive without it." (PMID 34282051, 2021). "However, the sample set of 8 early-stage (I and II) pancreatic cancer plasma samples had no detectable KRAS mutant cfDNA." (PMID 33420235, 2021). "Interestingly, ectopic GLI1 expression in KRAS-expressing mice enhanced IKBKE expression and nuclear RelA staining, and the knockdown of IKBKE expression in pancreatic cancer cell lines impaired their ability to grow in soft agar and induced apoptosis by caspase 3 cleavage." (PMID 34572373, 2021). "Notably, these correlations were independent of tumor histological subsites, and are in line with previous reports suggesting that DCLK1 is involved in regulating of the NOTCH, KRAS, WNT, and TGFβ pathways to promote progression, EMT, and self-renewal in colorectal and pancreatic cancer cells." (PMID 34336664, 2021). "Under specific conditions such as the maintenance of human and mouse pancreatic cancer cells in culture, this is also true for mutant KRAS, which is not strictly required for cancer cell survival in vitro as long as these cells also possess a wild-type KRAS allele." (PMID 34491463, 2021). "PAS vaccination in a precancerous KRAS murine model demonstrated that PAS not only decreases pancreatic fibrosis and alters the immune cell signature of the tumor microenvironment but that it also decreases proliferation and progression on precancerous PanIN lesions preventing pancreatic cancer." (PMID 34926305, 2021). "Gene expression signature of KRAS mutant pancreatic cancer is not defined." (PMID 32725342, 2020). "This combination has been explored in patients with EGFR mutant pretreated NSCLC, triple-negative breast cancer, pancreatic cancer, colorectal cancer, malignant melanoma, NSCLC and other advanced solid tumors with KRAS, NRAS and/or B-RAF mutations; the results are not available yet." (PMID 32560574, 2020).
pancreatic cancer (continued). "Furthermore, some KRAS-driven overexpressed enzymes, such as RPIA, are still preserved in some pancreatic cancer cell lines with KRAS ablation, sustaining nonoxidative PPP and cancer cell survival in a KRAS-independent manner." (PMID 32122374, 2020). "In surviving cells after KRAS inactivation, transcriptome analysis revealed that expression of genes involved in mitochondrial function, such as ETC and β-oxidation, is increased, and mitochondria have a larger size and consume more oxygen than bulk pancreatic tumor cells." (PMID 32674438, 2020). "Increase in non-oxidative PPP activity supports the growth of KRAS-transformed pancreatic tumors." (PMID 31288436, 2019). "Because U1 Adaptor is a new generation gene silencing technology that may serve as a new therapeutic modality for targeting any oncogene, U1 Adaptors were translated to target KRAS and MYC, and the adaptors strongly inhibit pancreatic cancer cell proliferation." (PMID 31346334, 2019). "Unlike >90% of pancreatic tumours and cell lines that have activating mutations in KRAS8,30, PL18 has a wild-type KRAS allele, but retained potent sensitivity to downstream MEK (mitogen-activated protein kinase kinase) pathway inhibitors trametinib and PD0325901." (PMID 31097696, 2019). "Here they show glycogen synthase kinase 3 (GSK3) to be required for the growth and survival of human mutant KRas-dependent tumors but dispensable for mutant KRas-independent tumors and show GSK3 inhibition to inhibit in vivo growth of Kras mutant patient-derived pancreatic tumors." (PMID 30514931, 2018). "Importantly, blockade of PI3K or PDK1 activity elicited a marked inhibition of KRAS-dependent metaplasia and tumorigenesis, thus suggesting also that the KRAS→PI3K→PDK1 pathway may represent a potentially important target in pancreatic cancer therapy." (PMID 29156578, 2017). "Although RNA interference (RNAi) provides an alternative therapeutic approach for inhibiting KRAS gene function, the efficientdelivery of siRNAs remains a problem and early attempts to develop small molecules targeting KRAS as a direct pancreatic cancer therapy were not successful." (PMID 27322423, 2016). "Specifically, the present study further reveals that lncRNA-NUTF2P3-001 is upregulated in pancreatic cancer cells under hypoxia and CoCl2 treatment, which is attributed to the binding of hypoxia-inducible factor-1α (HIF-1α) to hypoxia response elements (HREs) in the upstream of KRAS promoter." (PMID 26755660, 2016). "Son and his colleagues had proved that GOT1 mediates the utilization of glutamine in pancreatic cancer; oncogenic KRAS coordinates the shift from canonical type to non-canonical type of glutamine-dependent metabolism by increasing expression of GOT1 and decreasing expression of GLUD1." (PMID 25719198, 2015). "Therefore, despite our current classification system, KRAS may not be actionable target, at least not simply targetable with single agent targeted therapy, in many diseases, including those in which the mutations occur in high proportion (e.g. pancreatic cancer)." (PMID 26015395, 2015). "Detection of RBM5 and KRAS expression by quantitative reverse transcription-polymerase chain reaction (qRT-PCR) and western blotting was performed at mRNA and protein levels, respectively, in pancreatic cancer and non-tumor tissues." (PMID 23425895, 2013).
pancreatic cancer (continued). "Differently, a recent study performed in genetically engineered mouse models of solid tumors, among them KRAS driven pancreatic cancer, did not confirm an increased metastases frequency in anti-VEGF antibody treated mice, neither in monotherapy nor in combined therapy with gemcitabine." (PMID 23641216, 2013). "Deferasirox (DFX), an iron chelator, was also found to have an antiproliferative effect on pancreatic cancer cells via the suppression of FTH1 expression, suggesting that FTH1 expression or activity may be exploited as an effective therapeutic tool to target KRAS-mutant PDAC." (PMID 39294443, 2024). "In PDAC and CRC, a study found that resistance to anti-KRAS therapy may be driven by deubiquitinase USP21, which promotes KRAS-independent tumor growth by regulating MARK3-induced macrophagocytosis, and thus, USP21 may serve as a new target for the treatment of pancreatic cancer." (PMID 36675641, 2023). "Their findings suggest a novelty for the cannabinoids in which KRAS, an undruggable target expressed in many lethal cancers can be supressed through targeting PAK1 and the suppression of PDL-1 could be enhanced for immune checkpoint blockade therapy in pancreatic cancers." (PMID 34259916, 2021). "Moreover, in an isogenic pancreatic cancer cell line with CRISPR-Cas9-mediated knockout of SHP2, tyrosyl phosphorylation of endogenous KRAS Q61H was observed even in the absence of EGF treatment, which is consistent with the notion that SHP2 is involved in dephosphorylating endogenous KRAS." (PMID 34725361, 2021). "Thus, we propose that the established KRAS-initiated pancreatic cancer model, generated by use of the combination of CRE/Lox and GAL4/UAS systems, now provides a preclinical platform to test various strategies for pancreatic cancer and finally improve outcomes for pancreatic cancer patients." (PMID 30533257, 2018). "More importantly, downregulation of KRAS and its downstream proteins, p-AKT and p-ERK, were detected after NUTF2P3-001-siRNA transfection, indicating that the lncRNA-NUTF2P3-001 acted as promoter in pancreatic cancer in vitro and might play a role via regulating KRAS and its downstream pathways." (PMID 26755660, 2016). "In addition to TGFβ and KRAS activation, epidermal growth factor receptor (EGFR) signaling, a cascade aberrantly activated in the majority of PDACs, has been demonstrated to play a critical role in HH/GLI1-regulated tumor-initiating pancreatic cancer cells (Eberlet al., 2012)." (PMID 25352983, 2014). "Therefore targeting ERK in pancreatic cancer patients will not specifically block signals from Trop2, but would rather block a number of signals which result in the activation of ERK such as those induced by KRAS mutations." (PMID 20858281, 2010). "Conditional deletion of Lifr reduces pancreatic tumor progression, but not ADM formation or tumor initiation in an oncogenic KRAS mouse model (Pdx1-Cre; lox-stop-lox-KrasG12D/+; Trp53lox/lox; Lifrlox/lox; lox-stop-lox-Rosa26Luc/Luc)." (PMID 35159011, 2022). "Additionally, oncogenic KRAS-induced NRF2 could upregulate the expression of glutaminase-1, glutamate oxaloacetate transaminase 1, and cystine/glutamate antiporter SLC7A11 to enhance glutaminolysis and antioxidant capacity, leading to chemoresistance in KRAS-driven pancreatic cancer." (PMID 35681705, 2022).